SLC2A1 (solute carrier family 2 member 1)
Description:
Facilitative glucose transporter, which is responsible for constitutive or basal glucose uptake. Has a very broad substrate specificity; can transport a wide range of aldoses including both pentoses and hexoses. Most important energy carrier of the brain: present at the blood-brain barrier and assures the energy-independent, facilitative transport of glucose into the brain. In association with BSG and NXNL1, promotes retinal cone survival by increasing glucose uptake into photoreceptors (By similarity). Required for mesendoderm differentiation (By similarity).
Synonyms: GLUT-1; GLUT1; DYT18; DYT9; CSE; DYT17; EIG12; GLUT; GLUT1DS; HTLVR; PED; SDCHCN
Tractability: Small molecule: a structure with a bound ligand is known; a high-quality ligand is known; it belongs to a druggable protein family. Antibody: UniProt places it where antibodies can reach, with high confidence; its Gene Ontology location is reachable by antibodies, with high confidence; UniProt predicts a signal peptide or a membrane-spanning region; the Human Protein Atlas places it where antibodies can reach. PROTAC: ubiquitination databases record sites on it; its protein half-life has been measured; a small molecule that binds it is known.
Target class: SLC superfamily of solute carriers; Electrochemical transporter; SLC02 family of hexose and sugar alcohol transporters; Transporter
Chemical probes: BAY-876 (high quality)
Gene: Protein-coding gene on chromosome 1 (42,925,353 to 42,958,893, reverse strand). Ensembl gene ENSG00000117394.
Subcellular location: Cell membrane; Melanosome; Photoreceptor inner segment
Subcellular location (Human Protein Atlas): Plasma membrane; Centriolar satellite
Pathways (Reactome):
Metabolism: Lactose synthesis; Regulation of insulin secretion; Vitamin C (ascorbate) metabolism
Disease: Defective SLC2A1 causes GLUT1 deficiency syndrome 1 (GLUT1DS1)
Transport of small molecules: Cellular hexose transport
Gene Ontology:
Molecular function: D-glucose transmembrane transporter activity; dehydroascorbic acid transmembrane transporter activity; identical protein binding; long-chain fatty acid transmembrane transporter activity; protein binding; fucose transmembrane transporter activity; kinase binding; transmembrane transporter activity; xenobiotic transmembrane transporter activity
Biological process: central nervous system development; D-glucose import across plasma membrane; D-glucose transmembrane transport; long-chain fatty acid import across plasma membrane; photoreceptor cell maintenance; protein-containing complex assembly; transport across blood-brain barrier; dehydroascorbic acid transport; L-ascorbic acid metabolic process; response to insulin; cellular hyperosmotic response; cellular response to mechanical stimulus; cerebral cortex development; female pregnancy; fucose transmembrane transport; response to hypoxia; response to Thyroglobulin triiodothyronine; transmembrane transport; xenobiotic transport
Cellular component: apical plasma membrane; basolateral plasma membrane; blood microparticle; cortical actin cytoskeleton; extracellular exosome; glucose transporter complex; melanosome; membrane; midbody; plasma membrane; Golgi membrane; photoreceptor inner segment; sarcolemma; caveola; cell-cell junction; cytoplasm; cytosol; female pronucleus; intercalated disc; membrane raft; presynapse; synapse; vesicle; Z disc
Genetic constraint (gnomAD): Loss-of-function variants: 2 observed, 45.46 expected, observed/expected ratio (o/e) 0.044, 90% interval 0.017 to 0.14. The upper end of that interval is the gene's LOEUF score, 0.14, which puts it in group 1 of 6, group 1 being the genes least tolerant of losing a copy. Missense variants: 345 observed, 679.02 expected, observed/expected ratio (o/e) 0.51, 90% interval 0.46 to 0.56. Synonymous variants: 244 observed, 272.94 expected, observed/expected ratio (o/e) 0.89, 90% interval 0.8 to 0.99.
Gene-disease validity (ClinGen):
ClinGen rates the evidence that SLC2A1 causes each of these diseases.
GLUT1 deficiency syndrome (autosomal dominant): Definitive. An epileptic encephalopathy resulting from impaired glucose transport into the brain.
Homologues: Orthologues: chimpanzee SLC2A1 (99% identical), macaque SLC2A1 (99% identical), rat Slc2a1 (98% identical), pig SLC2A1 (98% identical), mouse Slc2a1 (97% identical), guinea pig SLC2A1 (95% identical), tropical clawed frog slc2a1 (82% identical), zebrafish slc2a1b (79% identical), zebrafish slc2a1a (74% identical), rabbit SLC2A1 (70% identical), Drosophila melanogaster sut1 (35% identical), Drosophila melanogaster CG7882 (35% identical), and 40 more. Paralogues in human: SLC2A4 (65% identical), SLC2A3 (64% identical), SLC2A14 (62% identical), SLC2A2 (56% identical), SLC2A5 (41% identical), SLC2A9 (39% identical), SLC2A7 (39% identical), SLC2A11 (36% identical), SLC2A13 (28% identical), SLC2A12 (27% identical), SLC2A10 (25% identical), SLC2A8 (25% identical), and 1 more.
Diseases named in the same sentence as SLC2A1 in open-access papers:
SLC2A1 is named in the same sentence as 694 diseases in open-access papers, as found by Europe PMC text mining. Sharing a sentence is not in itself a finding about the gene and the disease. The quoted sentences say what the papers report.
breast carcinoma (261 papers, 2002 to 2026). "The results showed that consistent with the results of bioinformatics and machine learning analysis, SLC2A1 is a breast cancer risk gene, and its knockdown can induce iron death of breast cancer cells and inhibit cancer cell growth." (PMID 38244591, 2024). "SLC2A1 is highly expressed in breast cancer and other tumor diseases and is closely associated with the progression and metastasis of various cancers." (PMID 38244591, 2024). "A prognostic model was constructed using these three genes, and the results showed that high expression of SLC2A1 is associated with poor prognosis in breast cancer patients, while low expression of TXNIP and ATF3 is associated with poor prognosis." (PMID 38244591, 2024). "Corresponding to our study, high expression of SLC2A1 has been found to be associated with inferior outcomes in various malignancies in adults, including pancreatic cancer, colorectal cancer, breast cancer, lung cancer, and others." (PMID 33810575, 2021). "Glucose influx in breast cancer tissue associated with SNPs in SLC2A1, the gene that encodes Glut1, was attributable to the rs841853 locus in 52 German caucasians with primary breast cancer." (PMID 29867928, 2018). "Knowing that XBP1s has already been reported as a co-activator of HIF-1α in the transcription of the gene encoding GLUT1 (SLC2A1) in breast cancer cells, it was tempting to speculate such a role in our model of proinflammatory macrophages." (PMID 37711626, 2023). "Together, these data suggest that GLUT1 is required for the early stages of Neu-induced mammary tumorigenesis, and that loss of only a single copy of Slc2a1 is sufficient to prevent the majority of Neu-induced mammary tumors." (PMID 27998284, 2016). "Gene-disease associations further prioritized G6PD, SLC2A1, and TK1 as robust targets strongly linked to lung and breast cancers." (PMID 42241400, 2026). "Glut1 expression is elevated in breast cancer, with the TCGA dataset showing increased levels of GLUT1 (SLC2A1) in luminal, HER2-positive, and triple-negative breast cancer." (PMID 40713647, 2025). "Inhibition of SLC2A1 can suppress the glycolysis process, cell proliferation, migration, and metastasis of breast cancer cells." (PMID 38244591, 2024). "In summary, the three key ferroptosis-related genes (TXNIP, SLC2A1, ATF3) are closely associated with the development and prognosis of breast cancer." (PMID 38244591, 2024). "Downregulation of SLC2A1 expression promoted ferroptosis and suppressed tumor cell growth in breast cancer cells (P < 0.01), while overexpression of TXNIP or ATF3 had the same effect (P < 0.01)." (PMID 38244591, 2024). "This study identified three key ferroptosis-related genes (TXNIP, SLC2A1, ATF3) associated with breast cancer by integrating bioinformatics analysis and multiple machine learning algorithms, and preliminarily validated their roles through cell experiments." (PMID 38244591, 2024). "Among them, TXNIP and ATF3 were significantly downregulated in breast cancer tissues compared to adjacent tissues (P < 0.001), while SLC2A1 was significantly upregulated in breast cancer tissues compared to adjacent tissues (P < 0.001)." (PMID 38244591, 2024). "Our results suggest that patients with decreased SLC2A1 expression have a decreased OS and relapse-free survival rates for luminal A subtypes of breast cancer." (PMID 37108300, 2023). "We then analyzed SLC2A1 mRNA expression using BRCA (Breast Cancer) datasets and TCGA breast cancer datasets (FDR = 1.9 × 10−11) and the GEPIA database." (PMID 37108300, 2023). "We then analyzed the relationship between SLC2A1 expression and survival outcomes in patients with breast cancer." (PMID 37108300, 2023). "To investigate their regulatory relationships, we summarized the capacity for which SLC2A1 mRNA expression has a potential effect on pathway activity in breast cancer." (PMID 37108300, 2023).
breast carcinoma (continued). "CADD522 negatively regulated RUNX2 target gene transcription including MMP13, VEGF and SLC2A1 in breast cancer cells." (PMID 36936386, 2023). "Oncomine database analysis indicated that SLC2A1 expression was higher in bladder cancer, breast cancer, CRC, esophageal cancer, kidney cancer, leukemia, lung cancer, ovarian cancer, and pancreatic cancer than in normal tissues." (PMID 35399515, 2022). "Some studies also found that the expression of SLC2A1 in breast cancer, esophageal cancer, and leukemia was lower than that in normal samples." (PMID 35399515, 2022). "Many malignant tumors, including pancreatic cancer, breast cancer, and prostate cancer have up-regulated SLC2A1, and the level of SLC2A1 is closely related to the clinical stage, degree of differentiation and lymph node metastasis of pancreatic cancer." (PMID 36685915, 2022). "Combination of SLC2A1 inhibitor and cisplatin or paclitaxel displayed synergistic therapeutic effects in lung and breast cancers." (PMID 33664854, 2021). "The GEPIA (Gene Expression Profiling Interactive Analysis) dataset was used to compare the mRNA expression of SLC2A1–4 between breast cancer and normal tissue samples." (PMID 34525987, 2021). "GLUT1 is encoded by the SLC2A1 gene and plays an important role in the development of many tumors, such as nonsmall cell lung cancer 17 and breast cancer." (PMID 34475997, 2021). "In our study, the mRNA expression of SLC2A1 was significantly higher in breast cancer, while the expression levels of SLC2A2–4 were downregulated." (PMID 34525987, 2021). "As is shown in the figure, 10 out of 53 analyses (4 out of 14 datasets) revealed SLC2A1 upregulation in breast cancer, while 1 out of 53 analyses (1 out of 14 datasets) displayed SLC2A1 downregulation." (PMID 34525987, 2021). "According to the results, the mRNA expression of SLC2A1 was significantly higher in breast cancer, while the expression levels of SLC2A2–4 were downregulated." (PMID 34525987, 2021). "There is an inverse relationship between the expression level of miR-140-5p and SLC2A1 in breast cancer patient samples." (PMID 31138773, 2019). "GLUT1 (SLC2A1) is expressed in breast cancer cells and is likely responsible for avid glucose uptake observed in established tumors." (PMID 27998284, 2016). "SLC2A1 is over-expressed in several different types of carcinomas, including liver, lung, endometrial, oral and breast cancers, as well as gastric cancer." (PMID 26193257, 2015). "Following SLC2A1 knockout in A549 cells, E-cadherin displayed a significant downregulation, while N-cadherin exhibited upregulation, consistent with previous findings in breast cancer." (PMID 40824962, 2025). "Additionally, inhibition of SLC2A1 can increase autophagic flux to suppress tamoxifen resistance in breast cancer cells." (PMID 38244591, 2024). "High expression of SLC2A1 has been found to be connected with inferior outcomes in various adult malignancies, including liver cancer, lung cancer, breast cancer, colorectal cancer, and so on." (PMID 35938001, 2022). "We showed that the SLC2A1 gene was hypomethylated and upregulated in human breast cancer tissues." (PMID 35622738, 2022). "Concurrently, SLC2A1 was significantly up-regulatedin breast cancer." (PMID 34488531, 2021). "In addition, SLC2A1 was found to be upregulated in a variety of tumors, including liver cancer, breast cancer, lung cancer, and so on." (PMID 34977159, 2021). "SLC2A1, 3, 4, 6, 8, 9, 10 and 12 were significantly dysregulated in breast cancer (p <0.01)." (PMID 34488531, 2021). "For example, solute carrier family 2 member 1 (SLC2A1), also called GLUT1, a glucose transporter involved in the first step of glycolysis, is a direct target of miR-22 in breast cancer, and miR-22 dysregulation can inhibit cell proliferation and invasion via GLUT1." (PMID 34496868, 2021). "The mRNA expression of SLC2A1 was significantly higher in breast cancer." (PMID 34525987, 2021).
breast carcinoma (continued). "Among them SLC2A1, 3, 4 and 14 has the most data available in breast cancer." (PMID 34488531, 2021). "In breast cancer, SLC2A1 expression was closely correlated with higher tumor grade." (PMID 26193257, 2015). "For instance, increased levels of SLC2A1 have been considered a potential prognostic marker for LUAD, colorectal cancer, and breast cancer." (PMID 40824962, 2025). "To investigate the effects of key ferroptosis-related genes (TXNIP, SLC2A1, and ATF3) on ferroptosis in breast cancer cells, we measured the levels of GSH, MDA, and Fe2+ in the cells." (PMID 38244591, 2024). "Three key ferroptosis-related genes (TXNIP, SLC2A1, ATF3) closely related to the occurrence, development, and prognosis of breast cancer were identified using machine learning algorithms." (PMID 38244591, 2024). "For the first time in this study, we used a comprehensive in silico approach and identified five proto-oncogenes (TUBA1B, SLC2A1, PGK1, CCND1, and NCAPD2) and two tumor suppressor genes (RPLP2, RPL37) as novel therapeutic targets against breast cancer." (PMID 35622738, 2022). "In this study, for the first time, we report five oncogenes (TUBA1B, SLC2A1, PGK1, CCND1, and NCAPD2) and two tumor suppressors’ genes (RPLP2, RPL37) as novel therapeutic targets in breast cancer." (PMID 35622738, 2022). "TUBA1B, SLC2A1, PGK1, CCND1, and NCAPD2 have been overexpressed in breast cancer tissues and their promoter region was hypomethylated (The graph on top shows gene expression and the graph at the bottom shows methylation beta value)." (PMID 35622738, 2022). "Here, we used GEPIA and LinkedOmics databases to investigate the prognostic value of SLC2A1–4 and RB1 gene expression in breast cancer." (PMID 34525987, 2021). "The present study is the first to explore the relationship of mRNA expression between SLC2A1–4 and RB1, and to study the prognostic values of GLUT1–4 in breast cancer using data mining methods." (PMID 34525987, 2021). "SLC2A1 and SLCA2A3 mRNAs expression was found, respectively in 100% and 97.4% samples of endometrial cancers and only in 50% and 40% samples of breast cancers." (PMID 22270867, 2012). "Therefore, SLC2A1 and PPIG both appear to be significant prognostic markers in patients with HER2-positive breast cancer." (PMID 40004024, 2025). "It was demonstrated that knocking-down HIF-2α in MDA-MB-231 breast cancer cells significantly decreased the expression of glycolysis-related gene products, such as HK2, LDHA, SLC2A1 and PDK1, consisting with the suppression of mRNA levels of glycolysis- and hypoxia-related genes." (PMID 35096814, 2021). "In human breast cancers, SLC2A1 was higher in ductal carcinoma in situ compared to the normal breast, but lower in invasive versus in situ lesions, suggesting the requirement for GLUT1 decreases as tumors progress." (PMID 27998284, 2016). "However, it is still unclear whether TXNIP, SLC2A1, and ATF3 affect the growth of breast cancer cells by regulating the ferroptosis mechanism." (PMID 38244591, 2024). "SLC2A1–4 expression level does not have a significant influence on the OS in breast cancer." (PMID 34525987, 2021). "Finally, we investigated whether there was any link between the expression of WSB1 and HIF targets SLC2A1, VEGFA, CA9, and HK2 in breast cancer patients." (PMID 29540773, 2018). "It is also plausible that WSB-1 could regulate the expression of only a selected number of HIF target genes, rather than all HIF-dependent expression, as it is the case in breast cancer, respectively, for co-factors p300 and DEK for GLUT-1 (SLC2A1) and VEGF (VEGFA) expression." (PMID 29540773, 2018). "Similarly, in MCF7 breast cancer cells SLC2A1, HK2, and PFKFB3 but not ENO1 or LDHA were strongly induced by hypoxia." (PMID 23866118, 2013).
breast carcinoma (continued). "Using transcriptome sequencing data of the CSC subpopulation in SUM149 human breast cancer cell line from GSE132083, we compared the glycolytic gene expression profiles between the CSC group and non-CSC group, and found that SLC2A1, HK2, ALDOA, ENO1, LDHA and PDK1 were upregulated in the CSC group." (PMID 34052833, 2021).